INS (insulin)
Diseases named in the same sentence as INS in open-access papers (continued):
Sharing a sentence is not in itself a finding about the gene and the disease.
diabetes (continued). "During the last few decades, a massive range of mathematical models, computer algorithms and statistical methods have been proposed in order to understand different aspects of diabetes, such as glucose metabolism, insulin kinetics, β-cell mass, and the glucose-insulin regulatory system." (PMID 23554650, 2010). "In a model consisting of the number of childhood adverse life events, diagnosis of diabetes, BMI, and blood glucose and insulin levels, the number of childhood adverse life events was the only factor explaining the shorter telomere length (β = −0.085, se = 0.031, P = 0.006)." (PMID 20520834, 2010). "The primary objective of this study was to identify the relationships among expectations about insulin therapy, experiences with insulin therapy, and diabetes treatment satisfaction in a sample of insulin-naïve patients with type 2 diabetes who experienced an insulin therapy." (PMID 20370840, 2010). "Thus, the increasing need of aggressive diabetes treatment has led to the improvement of insulin therapy and its implementation techniques." (PMID 20589066, 2010). "Interestingly, FOXO1 in diabetes is mostly known for its effect on insulin regulation of glucose production and insulin sensitivity." (PMID 20300563, 2010). "During conditions of identical glucose and insulin concentrations, mean aqueous flow was lower by 0.58 μl/min in the diabetes group compared to controls (2.58 ± 0.65 versus 3.16 ± 0.66 μl/min, respectively, mean ± SD, p = 0.07) but statistical significance was not reached." (PMID 20573241, 2010). "Diabetes mellitus is an evolutionary disease with progressive reduction in the number of β cells able to produce insulin, leading to insufficient secretion of the hormone and subsequent hyperglycemia, even in the presence of oral drugs and insulin therapy." (PMID 20718958, 2010). "The alterations in RV and LV insulin-stimulated glucose metabolism and systolic function may be attributed to ventricular interdependence, but also indicate that diabetes similarly affects both ventricles." (PMID 20550678, 2010). "Even more interesting are the observations that both drug families have been shown to increase insulin sensitivity, indicating that Ang II directly interferes with insulin-dependent metabolic pathways and therefore probably is involved in the etiology of diabetes." (PMID 20383279, 2010). "For diabetes-related medications, two categories were found to be significantly associated with K6 scores, oral hypoglycemics and antihyperlipidemics, but not insulin." (PMID 20973956, 2010). "Most usually, it is the addition of other cardiovascular risk factors, like BP and hyperLDL/HDLemia which have strengthened the cluster in regard to its prediction of macrovascular disease; or of insulin or its sensitivity when it comes to pre-diabetes or diabetes." (PMID 20513248, 2010). "Research Question 3: How does diabetes treatment satisfaction differ among those individuals whose expectations about insulin therapy are exceeded by experiences with insulin therapy when compared with those whose expectations are met or those whose expectations are not met?" (PMID 20370840, 2010). "In this observational study we compared the barriers to insulin therapy and more generic quality of life aspects among insulin-treated and insulin-naïve type 2 diabetic patients who had poor glycaemic control at baseline and three months after an intensification of diabetes treatment." (PMID 20920319, 2010). "Fasting glucose level may reflect abnormalities in insulin sensitivity and beta cell function, and is a useful clinical indicator of diabetes." (PMID 20929593, 2010). "Diabetes was produced in rabbits by injection of the toxic glucose analogue alloxan, which selectively enters pancreatic beta cells and irreversibly decreases insulin production, similar to streptozotocin." (PMID 20819221, 2010).
diabetes (continued). "UAG down-regulated gene sets relating to fatty acid, cholesterol/steroid and glucose/carbohydrate metabolism, and mitochondrial respiration (OXPHOS and Krebs/TCA cycle pathways), as well as gene sets linked with T2D and Maturity Onset Diabetes of the Young (MODY), and insulin signaling." (PMID 20668691, 2010). "Hopefully, the identification of other novel natural products that significantly modulate insulin and/or pdx1 promoter activity will point to new methods of controlling beta-cell function and fate and eventually to new diabetes therapeutics based on the lead structures of these natural products." (PMID 20886041, 2010). "In the Cox regression model, medical admission, higher SAPS II score, older age comorbid liver cirrhosis, and mechanical ventilation on admission, but not a history of insulin-treated diabetes, were associated with an increased risk of death at 28 days." (PMID 20132545, 2010). "In the first case, diabetes education or better instructions about insulin treatment could be powerful tools to help type 2 diabetic patients coping better with the challenges of insulin therapy and changing their negative appraisal of this treatment option." (PMID 20920319, 2010). "Insulin also appears to be important in regulating the utilization of ketone bodies as the uptake of β-hydroxybutyrate and acetate by sheep hind limbs is impaired during alloxan diabetes and restored by insulin." (PMID 20613964, 2010). "Furthermore, imatinib therapy in CML patients with diabetes improves insulin sensitivity and fasting blood glucose levels." (PMID 19693287, 2009). "Regarding other protocols, in a study of cardiac surgery patients with diabetes, 61% of patients achieved the glucose target range of 4.4 to 8.3 mmol/L while on continuous insulin infusion based on the Portland protocol (paper-based) with a 7.1% hypoglycemia rate (BG <2.2 mmol/L)." (PMID 19822000, 2009). "A significant percentage of patients who develop melioidosis have preexisting diabetes mellitus, a hypothesis was presented that insulin may modulate the physiology of Burkholderia pseudomallei." (PMID 22399982, 2009). "Diabetes results from insufficient (absolute or relative) insulin secretion." (PMID 19135240, 2009). "The diabetes-induced slower HR and lower CO were reversed by 1 week of insulin treatment." (PMID 19706162, 2009). "Vadheim and Rotter suggested that clinical differences in the diabetic syndromes between ethnic groups and marked differences between normal plasma glucose and insulin concentrations between different populations indicate the heterogenicity of type 2 diabetes mellitus." (PMID 20062558, 2009). "The self-titration of insulin supported by an internet programme is based on the patient empowerment approach, defined as 'helping people to discover and use their own ability to gain mastery over their diabetes'." (PMID 19508712, 2009). "Concentrations of inflammatory biomarkers, plasma insulin and index of insulin resistance were associated with sleep quality for the total population and among a subgroup of participants that were free from CVD and diabetes." (PMID 19426521, 2009). "Similarly, data from our laboratory demonstrated that insulin treatment attenuates diabetes-induced mitochondrial alterations by improving the OXPHOS efficiency and protecting against the increase in oxidative stress." (PMID 27713238, 2009). "With no firm evidence to link the use of insulin (or any other diabetes therapy) to increased cancer risk this has not been addressed in this analysis." (PMID 19804622, 2009). "Bezafibrate leads to considerable raising of HDL cholesterol and reduces triglycerides, improves insulin sensitivity and reduces blood glucose level, significantly lowering the incidence of cardiovascular events and new diabetes in patients with features of the metabolic syndrome." (PMID 19619327, 2009).
diabetes (continued). "Furthermore, the diabetes-associated C-allele of TSPAN8 rs7961581 associated with decreased levels of CIR, AUC-insulin/AUC-glucose ratio, and the insulinogenic index." (PMID 19789630, 2009). "Diabetes mellitus is an endocrine disorder of carbohydrate metabolism resulting primarily from inadequate insulin release (Type I insulin-dependent diabetes mellitus) or insulin insensitivity coupled with inadequate compensatory insulin release (Type II non-insulin-dependent diabetes mellitus)." (PMID 19903331, 2009). "Type 1 Diabetes Mellitus (T1DM) is an autoimmune disease characterized by insulin deficiency and the loss of glycemia control, and is caused by the T-cell mediated destruction of pancreatic insulin-producing ß cells." (PMID 19287497, 2009). "Diabetes may be insulin-dependent, which is typically of early onset, or non insulin-dependent, when the body cannot effectively use the insulin it produces (maturity onset diabetes)." (PMID 19506713, 2009). "Insulin-resistant children at a younger age who can compensate by hyperinsulinemia may escape diabetes, but are still prone to other complications." (PMID 21274310, 2009). "Thiazolidinediones (TZDs) - strong synthetic PPARγ agonists used in diabetes therapy to improve insulin sensitivity - induce weight gain whereas CLAs, natural PPARγ ligands, caused moderate weight loss in humans and in some studies reduced insulin sensitivity in an isomer specific way." (PMID 19689798, 2009). "Therefore, understanding how to prevent and treat diabetes requires an extensive knowledge of the regulation of insulin secretion." (PMID 19859528, 2009). "In the present study we have examined the association between abdominal fat distribution and peripheral (muscle)/hepatic sensitivity to insulin using the visceral to abdominal subcutaneous fat area ratio (VF/SF ratio) in male patients with type 2 diabetes mellitus." (PMID 19656356, 2009). "Insulin resistance persists for many decades before the manifestation of overt diabetes, so that parental insulin sensitivity could well serve as a representation of insulin resistance state." (PMID 20062558, 2009). "A 14 year old female with type 1 diabetes mellitus and a subcutaneous insulin pump was treated for diabetic ketoacidosis presumed secondary to dietary indiscretion, and then restarted her subcutaneous insulin pump after exchanging the tubing." (PMID 19918445, 2009). "Importantly, the recovery efficiency of the p21-overexpressing mice from streptozotocin-induced diabetes was significantly higher than control mice, which is embodied by better physiological quality and earlier emergence of insulin expressing cells." (PMID 20020058, 2009). "Numerous rodent studies have shown that EPA improves IR in several models of obesity and diabetes and elevated systemic concentrations of insulin-sensitizing adiponectin as well as an improved response to a glucose load were reported in mice fed high fat diets enriched in EPA+DHA." (PMID 19664246, 2009). "Animal models have shown that insulin therapy is effective in diabetes." (PMID 20142874, 2009). "We are confident that the described association between NR4A3 genetic variants and insulin secretion is not a by-chance finding, and that further research on the role of orphan nuclear receptors in beta cell function and diabetes pathogenesis is warranted." (PMID 19682370, 2009). "Diabetes is characterized by progressive failure of insulin producing beta cells." (PMID 19463182, 2009). "Non-neuronal, peripheral serotonin deficiency causes diabetes mellitus and identifies an intracellular role for serotonin in the regulation of insulin secretion." (PMID 19859528, 2009). "Given the family of PI3K inhibitors could impact such general processes as insulin signaling, diabetes, obesity, and aging, unwanted side-effects should be carefully considered." (PMID 19293927, 2009).
diabetes (continued). "It was developed for the prediction of cardiac risk based on six independent prognostic factors: high-risk surgery, ischemic heart disease, congestive heart disease, history of cerebrovascular disease, insulin therapy for diabetes, and preoperative Scr higher than 2.0 mg/dL." (PMID 19463152, 2009). "Further support for the diabetes in the R6/2 mice being caused by impairment in insulin release rather than insulin insensitivity has been generated by the administration of pharmacological agents." (PMID 19956633, 2009). "The starting-point for treatment of diabetes is to investigate if the absence of regular insulin periodicity can be attributed to deficient β-cell rhythm or co-ordination." (PMID 19961265, 2009). "We describe an interesting case of a patient who presented acutely with unprovoked severe hyperglycaemic hyperosmolar state and was subsequently diagnosed with type 2 diabetes mellitus on a background of only impaired first phase insulin secretion 4 months prior." (PMID 19918352, 2009). "Lower concentrations of inflammatory biomarkers, plasma insulin and index of insulin resistance were associated with good levels of SRH for the total population and among a subgroup of participants that were free from cancer, CVD and diabetes." (PMID 19788754, 2009). "Insulin and oral hypoglycemic agents are the most widely used drugs for lowering blood sugar in diabetes, but these drugs also have various side effects such as hypoglycemia, weight gain (sulfonylurea), and lactic acidosis (biguanides), and all of these drugs can causes liver and renal damage." (PMID 20523870, 2009). "This is consistent with observations that prion infection affects insulin and insulin-like growth factor receptors in cell lines and that scrapie infection induced diabetes mellitus in hamsters is directly damaging the central nervous system, without affecting the pancreas." (PMID 20011040, 2009). "One hundred and eleven (31.7%) patients were taking injection insulin to treat their diabetes." (PMID 19574698, 2009). "However, in a large subset of obese and insulin-resistant individuals, these compensatory mechanisms are impaired, leading to reduced β cell mass and function and culminating in manifest diabetes." (PMID 19135240, 2009). "Insulin and oral hypoglycemics are the most widely used drugs for diabetes but they also have various side effects like hypoglycemia, weight gain (sulfonylurea), lactic acidosis with biguinides and all of these drugs may cause liver and renal damage." (PMID 20177576, 2009). "Genes involved in the cell cycle and apoptosis of β-cells might play a role in diabetes by dysregulating the response of β-cells when a higher insulin output is called for when insulin resistance is present." (PMID 19794883, 2009). "As excess body fat leads to high levels of insulin (and eventually to diabetes) and as diabetes is a proxy measure for hyperinsulinaemia, the inclusion of terms for both of these factors in the same model may underestimate the real effect of hyperinsulinaemia." (PMID 19190630, 2009). "Diabetes mellitus (DM) is characterized by hyperglycemia caused by a lack of insulin, insulin resistance, or both." (PMID 19936237, 2009). "Pilot studies have suggested that insulin therapy also delays diabetes in humans." (PMID 20142874, 2009). "These mutations result in either gain-of-function or loss-of-function of the receptor; human subjects bearing these mutations show decreased or increased lipid accumulation in adipose tissue, enhanced insulin sensitivity or insulin resistance, dyslipidemia, diabetes, and hypertension." (PMID 19390629, 2009). "Thus, the consumption of probiotics confer protections to the well being of pancreatic β-cells that plays a significant role in the production of insulin molecules and prevents the onset of insulin dependent diabetes as well as diabetes-related hypertension." (PMID 19865517, 2009).
diabetes (continued). "There are no published reports on whether the biological effects of TCF7L2 gene on diabetes are partly via inflammation or whether inflammation alters the effects of TCF7L2 on insulin secretion and other metabolic traits." (PMID 19825152, 2009). "By considering only insulin effects we excluded the possibility that patients may have been prescribed one of the new classes of diabetes interventions (DPP-IV inhibitor or GLP-1 agonist) prior to initiating insulin." (PMID 19804622, 2009). "Under myocardial I/R injury, the capacity for Akt phosphorylation is impaired in insulin-deficient diabetes, and treatment of insulin failed to further induce the phosphorylation level of Akt." (PMID 19706162, 2009). "Interestingly, most diabetes genes detected by the GWA studies are also involved in insulin secretory function, as it is the case for NR4A3." (PMID 19682370, 2009). "Very little work has been carried out to assess the effect of diabetes on cyclosporine pharmacokinetics, although insulin and glucagon may regulate the metabolizing enzymes and/or transporters involved in cyclosporine disposition." (PMID 19859566, 2009). "Moreover, the proportion of βhigh and βlow-cells varied according to the insulin demand and was correlated with the progression of diabetes." (PMID 19440374, 2009). "Since SDT fatty rats might have weakness in pancreatic function, it is considered that the insulin secretion is deteriorated, and the incidence of diabetes in the rats cannot be suppressed by food restriction alone." (PMID 19696902, 2009). "In this kind of therapy, a simple endovenous injection is applied and a study of this was recently conducted with a group of 21 patients who were an average of 5 years old and had had diabetes an average of 9 months, paired with a control group of patients receiving usual insulin therapy." (PMID 19835616, 2009). "When we analyzed these associations among a subsample of the population who were free from CVD and diabetes, we found that significant associations remained for insulin, HOMA-IR, HOMA2-IR, LDL, TCH and TG (data not shown)." (PMID 19426521, 2009). "Perhaps in conditions of systemic insulin/insulin growth factor 1 (IGF-1) signaling reduction the metabolic syndromes (such as diabetes) that stem from the liver hide the potential health benefits of reduced insulin/IGF-1 signaling in other tissues, such as the brain." (PMID 27713238, 2009). "The obtained results revealed that males, patients with a longer history of diabetes, patients using insulin or oral medication for diabetes control, and patients with hypertension or nephropathy had a statistically significant increase in risk of any grade of DR as compared to other subjects." (PMID 19835608, 2009). "Our aim was to compare the effects of a Paleolithic ('Old Stone Age') diet and a diabetes diet as generally recommended on risk factors for cardiovascular disease in patients with type 2 diabetes not treated with insulin." (PMID 19604407, 2009). "Diabetes mellitus is a disorder caused by insufficient or absent production of the hormone 'insulin' by the pancreas." (PMID 19335903, 2009). "In this study, we established systemic in-vivo evidence from molecular to organism level to explain how diabetes can aggravate myocardial ischemia-reperfusion (I/R) injury and revealed the role of insulin signaling (with specific focus on Akt/GLUT4 signaling molecules)." (PMID 19706162, 2009). "Thus our results revealed the significance of central muscarinic receptor changes during diabetes and the regulatory role of insulin on muscarinic receptors." (PMID 19344500, 2009). "The Diabetes Control and Complications Trial (DCCT) was a 7-year longitudinal study that demonstrated the importance of the intensive insulin therapy when compared to conventional treatment in the development of chronic complications in patients with type 1 diabetes mellitus (T1DM)." (PMID 19835616, 2009).